TRBJ2-4 (T cell receptor beta joining 2-4)
Description:
J region of the variable domain of T cell receptor (TR) beta chain that participates in the antigen recognition. Alpha-beta T cell receptors are antigen specific receptors which are essential to the immune response and are present on the cell surface of T lymphocytes. Recognize peptide-major histocompatibility (MH) (pMH) complexes that are displayed by antigen presenting cells (APC), a prerequisite for efficient T cell adaptive immunity against pathogens. Binding of alpha-beta TR to pMH complex initiates TR-CD3 clustering on the cell surface and intracellular activation of LCK that phosphorylates the ITAM motifs of CD3G, CD3D, CD3E and CD247 enabling the recruitment of ZAP70. In turn ZAP70 phosphorylates LAT, which recruits numerous signaling molecules to form the LAT signalosome. The LAT signalosome propagates signal branching to three major signaling pathways, the calcium, the mitogen-activated protein kinase (MAPK) kinase and the nuclear factor NF-kappa-B (NF-kB) pathways, leading to the mobilization of transcription factors that are critical for gene expression and essential for T cell growth and differentiation. The T cell repertoire is generated in the thymus, by V-(D)-J rearrangement. This repertoire is then shaped by intrathymic selection events to generate a peripheral T cell pool of self-MH restricted, non-autoaggressive T cells. Post-thymic interaction of alpha-beta TR with the pMH complexes shapes TR structural and functional avidity.
Synonyms: TRBJ24; TCRBJ2S4
Gene: T-cell receptor joining (J) gene on chromosome 7 (142,796,998 to 142,797,047, forward strand). Ensembl gene ENSG00000211768.
Subcellular location: Cell membrane